MSLN (mesothelin)
Diseases named in the same sentence as MSLN in open-access papers (continued):
Sharing a sentence is not in itself a finding about the gene and the disease.
cancer (continued). "One of the most notable, mesothelin, is a glycosylphosphatidylinositol (GPI)-anchored cell surface glycoprotein overexpressed in many cancers." (PMID 35326701, 2022). "Amatuximab (MORAb-009), a monoclonal anti-ERC/mesothelin antibody, inhibits the interaction of ERC/mesothelin with CA125/MUC16 and reduces the cancer’s ability to invade other tissues." (PMID 35565327, 2022). "The binding of ERC/mesothelin to CA125/MUC16 enhances the migration and invasion of carcinoma cells." (PMID 35565327, 2022). "This mesothelin-targeting Lm-based vaccine (Lm-Mesothelin, CRS-207) was initially brought into the clinic in a Phase I trial with several cancer types that all express mesothelin, including PDAC." (PMID 33936058, 2021). "MSLN scFv (SS1) was used for the development of a recombinant immunotoxin and CAR-T therapy that targets MSLN-expressing cancer cells in preclinical models and clinical trials." (PMID 34577541, 2021). "The human anti-mesothelin antibody-drug conjugate, anetumab ravtansine (BAY 94-9343), has been developed as an anti-cancer therapeutic." (PMID 33546207, 2021). "The expression of mesothelin is also related to epithelial-mesenchymal transition (EMT) and cancer stem cells (CSCs)." (PMID 33637083, 2021). "In total 27 patients received cancer immunotherapy in second or further line (14 patients with anti-CTLA4, 8 patients with antiPD-1/PD-L1, 4 patients with anti-mesothelin and 1 patient with oncolytic virus)." (PMID 34725384, 2021). "Noteworthy, among the top-10 upregulated genes we found cancer-related genes such as FosB proto-oncogene (FOSB; logFC = 1.89), mesothelin (MSLN; logFC = 3.06), and arrestin beta 1 (ARRB1; logFC = 1.89)." (PMID 34439473, 2021). "Anti-MSLN antibodies can also block the binding of MSLN with MUC16 and inhibit the expansion and metastasis of cancer cells." (PMID 32061257, 2020). "In vitro studies illustrated that MORAb-009 kills cancer cells by ADCC and blocking mesothelin/MUC-16 interaction." (PMID 33344222, 2020). "Throughout this review, we focused on few GPI-anchored proteins (MSLN, Glypican-3, CEA, DAF, and MAC-i), with these proteins overexpressed in many cancers." (PMID 33344222, 2020). "Assuming that MSLN is related to the process of carcinogenesis and induces EMT, it is plausible that biopsy specimens taken from the cancer surface can be used for the preoperative detection of CRC with high malignancy potential." (PMID 33196692, 2020). "Because MSLN is a highly specific antigen in several cancers, CAR-T therapy has been proven to be a promising strategy for the treatment of these cancers." (PMID 31463062, 2019). "In summary, these results confirm that MSLN is highly expressed in HGC-27 and SKOV-3 cell lines as well as in the corresponding cancer tissues." (PMID 31209210, 2019). "Mesothelin (MSLN), the second most frequently targeted biomarker after CD19, has emerged as an attractive target for cancer immunotherapy." (PMID 30031396, 2018). "Of the non-T-cell related targets, the proteins currently most widely targeted are ERBB2 (HER2), EGFR, MS4A1 (CD20), CD22, PDCD1 (PD-1), MSLN (mesothelin), and ERBB3 (Her3), all for cancer indications." (PMID 28822103, 2018). "At a concentration of 2 μM, mFc evidently bound to all eight tested viral proteins and cancer-related antigens, including HIV-1 gp140, Zika virus (ZIKV) envelope protein domain II (EDII), domain III (EDIII), mesothelin, 5T4, PD-L1, OX40, TIM-3." (PMID 29181008, 2017). "Knocking down Hck substantially enhanced killing of cancer cells by the drug, SS1P, which is a recombinant immunotoxin (RIT) that targets mesothelin in mesothelin-transfected A431 cells." (PMID 26910280, 2016). "Taking the protein candidates with the highest (MSLN) and lowest (LEFTY1) expression in HGSC relative to the other histotypes and mapping these across other cancers revealed highly variable patterns of abundance between TCGA tissue type sets." (PMID 27713570, 2016).
cancer (continued). "The interaction between MSLN and CA125/MUC16 promotes cancer cell dissemination and correlates with poor prognosis in patients." (PMID 25672245, 2015). "On the contrary, MSLN overexpression has been observed in a wide range of cancers; diagnostics with PET probe made from anti-MSLN antibody has the potential to be applicable to a broad spectrum of cancers." (PMID 25883990, 2015). "Using genetic engineering, we designed the novel cancer drug Meso-TR3, a fusion protein between native mesothelin and TR3." (PMID 24447304, 2014). "In order to deliver TR3 selectively to MUC16-expressing cancers, we investigated the possibility of targeted TR3 delivery employing the high affinity mesothelin/MUC16 ligand/receptor interaction." (PMID 24447304, 2014). "Other recent studies from several cancer institutes have identified a number of promising biomarkers including HE4, mesothelin, and kallikreins." (PMID 24199600, 2013). "For instance, previous studies of MSLN and MUC4 defined positive labeling as focal antibody reactivity in more than 1% of cancer cells, while the present study required at least 10% of cells for an IHC score of 1+." (PMID 22792233, 2012). "MSLN and MUC1 were highly significant predictors of early cancer-specific mortality, and were superior to conventional pathologic features as prognostic markers." (PMID 22792233, 2012). "The methylation level of the LOH-H cancers was significantly lower at the 5'-transitional CpG sites of the VDR, FLJ43855, CDKN2A, MUC8, MAGEA2, and MSLN genes." (PMID 16827945, 2006). "In this study, we confirmed that MSLN, an elevated protein in liver preferential metastasis-derived cells, interacts with EGFR to activate downstream signaling pathways, thereby promoting cancer metastasis." (PMID 41513618, 2026). "Intraductal papillary mucinous neoplasm (IPMN) immunohistochemical investigation demonstrated that MSLN expression existed in cancer and adenoma cells, but not in normal pancreatic tissues." (PMID 40227616, 2025). "In this review, we provided an overview of MSLN biology and its role in each aspect of cancer development, from the establishment of an oncogenic TME to the enhancement of the metastatic features of cancer cells." (PMID 41335396, 2025). "The antigens folate receptor 1 (FOLR1) and mesothelin (MSLN) are specifically and highly expressed in cancer tissues, with only 11.25% of samples negative for both antigens." (PMID 40092990, 2025). "MSLN has been reported to facilitate both cell–cell and extracellular matrix adhesion by interacting with CA125, thereby promoting peritoneal dissemination in MSLN-overexpressing cancers." (PMID 41335396, 2025). "To evaluate the therapeutic potential of anti-MSLN Affitins, we designed BiKEs composed of either an Affitin monomer or dimer fused to an anti-CD16 VHH to activate natural killer cells toward hMSLN-expressing cancer cells." (PMID 41477550, 2025). "Successful preclinical NIR-PIT studies against cancer and cancer-stem like cell antigens have been performed against more than 20 different molecular targets expressed on different cancers including EGFR, HER2, PSMA, CD25, GPC3, mesothelin, CD133, CD44, CEA, DLL3, PD-L1, and others." (PMID 38658501, 2024). "Consistently, anti-Mesothelin CAR primary NK cells also exhibited greater cytotoxic effects against Mesothelin- and Mesothelin+ SiHa cells than CAR-T cells in the same experimental settings, indicating the dual nature of NK cells in the elimination of cancer cells." (PMID 39781381, 2024). "In conclusion, the novelty of the current study revolves around the identification of four HLA-A*02-restricted epitopes of MSLN and NCL with high binding affinity and complex stability, which rendered them as potential antigenic peptides for the production of anti-cancer T cells." (PMID 39294656, 2024).
cancer (continued). "Twenty coexpressed upregulated genes were identified from the GEO database, and we found FOLR1 (folate receptor 1) and MSLN (mesothelin) were specifically and highly expressed in cancer tissues and only 11.25% of samples were negative for both antigens." (PMID 34803504, 2021). "Mesothelin is a 40-kDa glycoprotein that is highly overexpressed in various types of cancers, however molecular mechanism of mesothelin has not been well-known." (PMID 33637083, 2021). "Some mesothelin monoclonal antibodies were reported as unable to inhibit cancer cell proliferation because the majority of these antibodies target N terminal region I rather than a key signaling domain in mesothelin." (PMID 33637083, 2021). "Knockdown of mesothelin upregulates epithelial and adhesion molecules on one side and on the other side that downregulates mesenchymal and CSC regulatory genes that relieves self-renewal, proliferation, dissemination and metastasis of cancer cells." (PMID 33637083, 2021). "No expression of integrin αvβ6, CEACAM5 and mesothelin was observed in fibrotic tissue, indicating these are potentially suitable targets for vital cancer cell identification after neoadjuvant therapy." (PMID 33004930, 2020). "No expression of MSLN was found in para-cancer tissues of the two antibodies, and the difference was statistically significant (χ2=40.615, p=0.000)." (PMID 32174772, 2020). "No expression of the two anti-MSLN antibodies was found in para-cancer tissues and the difference was statistically significant (χ2=40.615, p=0.000, p<0.05) when compared with PDAC tissues." (PMID 32174772, 2020). "Mesothelin is a 40-KD cell membrane glycoprotein, which presents on normal mesothelial cells and is highly expressed in different human cancers of the lung, endometrium, stomach and pancreas." (PMID 32731396, 2020). "When compared to PDAC, para-cancer tissues showed no MSLN expression using either EPR4509 or EPR19025-42 (p<0.05)." (PMID 32174772, 2020). "They took advantage of the co-expression of two TAAs, carcino-embryonic antigen (CEA) and mesothelin (MSLN) on AsPC-1pancreatic cancer cells, to generate dCARs containing two physically separate CEA-CD3ζ and MSLN-4/1BB signaling domains controlled with CEA and MSLN, respectively." (PMID 30937303, 2019). "Nonetheless, the essential transcriptional factor that regulates the MSLN overexpression in human cancers has not been identified." (PMID 30134520, 2018). "Transcription factors such as KLF6 and YAP1 have been investigated but binding of these factors are not adequate for MSLN overexpression in certain cancer types." (PMID 30134520, 2018). "Although not unidirectional, most of the observed differences (downregulation of proteins such as enolase 2, c-Met, mesothelin, PDGF-AA, eNOS, IL-6, and upregulation of CA125) suggested a negative impact of CDC-EVs on pathways associated with cancer." (PMID 29245929, 2017). "With respect to mesothelin-targeted therapies such as anti-mesothelin recombinant immunotoxin SS1P, chimeric anti-mesothelin monoclonal antibody MORAb-009, and mesothelin cancer vaccines CRS-207, investigators performed a lot of preclinical researches and opened a series of clinical trials." (PMID 28356156, 2017). "Even if we find mesothelin has little prognostic value in patients with TNBC, it may still be a promising target for novel drug therapies in other cancers." (PMID 27514374, 2016). "We have previously reported on Meso-TR3, a constitutive TRAIL trimer targeted to the biomarker MUC16 (CA125), in which the entire ectodomain of human mesothelin was genetically fused to the TR3 platform, facilitating attachment to the cancer cells via the MUC16 receptor." (PMID 27120790, 2016).
cancer (continued). "The fully humanized non-Region I anti-mesothelin antibody, hYP218, demonstrated adequate accumulation and internalization in mesothelin expressing cancer cells." (PMID 26981775, 2016). "Because the soluble form(s) of MSLN is present in very small amount (1.4–3.8 nmol/L), it should not interfere with antibody-based therapies that target the MSLN antigen on cancer cells." (PMID 25883990, 2015). "As MSLN is overexpressed in a wide range of cancers, anti-MSLN 11-25 mAb has the potential to become a PET imaging agent for detecting various kinds of MSLN-expressing cancers." (PMID 25883990, 2015). "Additionally, we found that (a) Mesothelin-specific T cell responses are significantly expanded in cancer patients (p = 0.0053), (b) the multifunctional CD4+ T cell response is directed toward a broad repertoire of epitopes within the Mesothelin protein." (PMID 24520352, 2014). "Among TNBC, MSLN was positive in 80 of 218 IDC-NOS and 2 out of 5 metaplastic carcinomas." (PMID 25506917, 2014). "In a multivariate model, MUC1 (odds ratio, OR = 28.95, 3+ vs. negative expression, p = 0.004) and MSLN (OR = 12.47, 3+ vs. negative expression, p = 0.01) were highly predictive of early cancer-specific death." (PMID 22792233, 2012). "Our study found that the elevated MSLN in hepatic metastatic TNBC could activate the EGFR as well as downstream ERK1/2 signaling pathways, thereby promoting the ability of cancer cells to survive and proliferate in the liver, and further contributing to the formation of hepatic metastases." (PMID 41513618, 2026). "The most recent data on this topic have shown that MSLN can also drive macrophage polarization towards an immunosuppressive phenotype characterized by the secretion of VEGFA, ARG1, and S100A9, thereby stimulating cancer cell growth and weakening the immune response." (PMID 41335396, 2025). "Likewise, non-transduced T cells, serving as negative control, exhibited negligible activity (i.e., <2% lysis) against the different target cancer cells, regardless of their mesothelin expression status." (PMID 40427042, 2025). "Furthermore, mesothelin, acting as a MUC16 functional partner in cancer development, may become more prone to bind with these mutant variants." (PMID 40478193, 2025). "Cancer cells expose cancer antigens on their surface, such as CA125 (MUC16) (cancer antigen 125), HE4 (human epididymis protein 4), WT1 (Wilms’ tumor 1), NY-ESO-1 (New York esophageal squamous cell carcinoma 1), or mesothelin, which T lymphocytes can recognize." (PMID 40362280, 2025). "In this context, studies conducted mostly on cancer cells revealed the presence of two essential motifs, an SP1-like and an MCAT, that drive gene expression and may contribute to the tissue-specificity observed for MSLN." (PMID 41335396, 2025). "Thus, the limited expression of mesothelin in non-essential tissues; high expression in cancers; and a presumed role in cancer progression; have made it an attractive target of cancer immunotherapies." (PMID 36911670, 2023). "Interestingly, normal pancreatic tissue does not express RNA coding for the precursor of mesothelin nor mesothelin protein, but it is overexpressed in several cancers, including PDAC." (PMID 35892707, 2022). "Accordingly, mesothelin may represent a novel target, complementary to HER2-based THVs, to be added to the growing arsenal of retargeted oncolytic viruses to treat breast as well as, in principle, any mesothelin-positive cancer." (PMID 33418877, 2021). "Of the 77 evaluated cancers, 18 were MSLN-positive (23.4%) and 59 were negative (76.6%)." (PMID 33196692, 2020).
cancer (continued). "Importantly, these findings implicate MSLN in a benign disease, indicating that the activation and role of MSLN is not restricted to cancer." (PMID 31222072, 2019). "The mechanisms of MSLN over-expression in cancer have not yet been elucidated." (PMID 28125734, 2017). "Soluble Meso-TR3 targets the cancer biomarker MUC16 in vitro and in vivo and exhibits all the positive features of a traditional TRAIL-based cancer drug, as well as enhanced stability, enhanced killing capacity and favorable 1:3 stoichiometry of targeting (mesothelin) and effector domain (TR3)." (PMID 24447304, 2014). "Similar to their results, we could not observe any significant differences in plasma MSLN levels between cancer and benign pancreatic disease patients." (PMID 24520352, 2014). "It is also worth noting that DU145 expresses some levels of mesothelin mRNA, but failed to express detectable levels of the protein at the cell surface, unlike 22Rv1-CR-1, suggesting differential protein trafficking or post-transcriptional regulation between these two carcinoma cell lines." (PMID 40427042, 2025). "Interestingly, the correlation between HOTAIR and MSLN is not been previously studied on any cell type, thus studying this correlation in TAMs highlights the importance of investigating this relationship in other cell types either cancer cells or immune cells." (PMID 36387279, 2022). "Unfortunately, the results of the phase II STELLAR trial, where the cancer vaccine GVAX, cyclophosphamide (CY) and CRS-207 (live, attenuated Listeria monocytogenes expressing mesothelin), evaluated with or without nivolumab, were disappointing (NCT02243371)." (PMID 35892707, 2022).
adenocarcinoma (25 papers, 2008 to 2025). A common cancer characterized by the presence of malignant glandular cells. "Though MSLN is expressed in almost all epithelioid MPM cases, it is also expressed at a significant percentage in adenocarcinomas (particularly in the lung), which results in the failing accuracy of MSLN as a diagnostic marker." (PMID 34439085, 2021). "The next target antigen tested for CAR-T therapy in NSCLC was mesothelin (MSLN) which expression is elevated in 69% of adenocarcinoma patients." (PMID 40428391, 2025). "We found that shed SDC-1 and MMP-7 levels were significantly lower, whereas Mesothelin and Galectin-1 levels were significantly higher in malignant mesothelioma effusions, compared to adenocarcinoma." (PMID 32731396, 2020). "In adenocarcinomas arising in the pancreas, stomach, and colorectum, MN-1 antibodies showed a more prominent mesothelin positivity rate than 5B2." (PMID 28460459, 2017).
hematological malignancies (10 papers, 2014 to 2025). "Clinically, CAR-NK therapies have advanced into Phase I/II trials for both hematologic malignancies and emerging solid tumor targets (e.g., CD19, mesothelin), with a favorable safety profile and transient in vivo persistence." (PMID 40723278, 2025). "CAR MΦs were generated by differentiation of genetically modified monocytes and showed increased phagocytosis against CD19+ hematological malignancies as well as HER2+ and Mesothelin+ solid tumor cells." (PMID 35326445, 2022).